GLP1R (glucagon like peptide 1 receptor)
Diseases named in the same sentence as GLP1R in open-access papers (continued):
Sharing a sentence is not in itself a finding about the gene and the disease.
metabolic disease (99 papers, 2010 to 2026). A congenital disorder (due to inherited enzyme abnormality) or acquired (due to failure of a metabolically important organ) disorder resulting from an abnormal metabolic process. "Understanding the cardioprotective properties of GLP-1R agonists may pave the way for their integration into cardiovascular risk management strategies, expanding their utility beyond metabolic disease and toward targeted microvascular therapy." (PMID 40243679, 2025). "Dysfunctional GLP-1R activation disrupts metabolic homeostasis, contributing to the pathogenesis of metabolic diseases." (PMID 40807391, 2025). "Finding novel drugs targeting this receptor and in combination with GLP-1R is pivotal to combat these metabolic diseases." (PMID 40280422, 2025). "Glucagon-like peptide-1 receptor agonists, originally developed for the treatment of metabolic disorders, have recently emerged as promising candidates for the management of substance use disorders." (PMID 40508146, 2025). "For instance, glucagon-like peptide-1 receptor agonists (GLP-1 RAs) have transformed the management of metabolic disease by reducing body weight." (PMID 41417444, 2025). "The wide distribution of the GLP-1R has allowed the study of semaglutide and liraglutide pharmacological protocols to improve metabolic diseases in several experimental models." (PMID 38742021, 2024). "Studies have shown that the brain expresses GLP-1R and GLP-1R agonists, which can regulate metabolic disorders and have the ability to access the blood–brain barrier." (PMID 39858999, 2024). "Here we demonstrate that the GLP-1R agonist liraglutide is highly effective at improving multiple aspects of metabolic disease in a mouse model of generalised lipodystrophy." (PMID 38745956, 2024). "Many novel therapeutics with extreme success in treating metabolic diseases are analogues of gut-derived peptide hormones, such as semaglutide, a glucagon-like peptide 1 (GLP1) receptor (GLP1R) agonist." (PMID 37590249, 2023). "The glucagon-like peptide-1 receptor (GLP-1R) has broad physiological roles and is a validated target for treatment of metabolic disorders." (PMID 35013280, 2022). "Establishing a consensus mechanism of action for biased GLP-1R agonists would help guide their development for the treatment of T2D and related metabolic diseases." (PMID 34129856, 2021). "This has implications for the ongoing development of affinity- versus efficacy-driven biased GLP-1R agonists as treatments for metabolic disease." (PMID 34129856, 2021). "Evaluation of models of metabolic disease and aging describe resistance to signaling through established GLP-1R+ circuits." (PMID 34660576, 2021). "Glucagon-like peptide-1 receptor (GLP-1R) agonists have attained blockbuster status as therapeutics in the area of metabolic diseases." (PMID 32481528, 2020). "GLP-1R imaging has potential in metabolic disease in human given its expression in human pancreatic islets and the incretin effect." (PMID 31903131, 2020). "To date, the majority of such agents being developed to treat metabolic diseases possess activity at the GLP-1R as the anchor pharmacophore but are also agonists for either the GIPR, the glucagon receptor, or both." (PMID 32730231, 2020). "Taken together, our data reveal an unprecedented opportunity for treating diet-induced metabolic disorders with parallel pharmacological targeting of GLP-1R and MC4R." (PMID 25652173, 2015). "The glucagon-like peptide-1 receptor (GLP-1R) and amylin analog pramlintide engage distinct yet complementary structural and functional features that define their protein–ligand interactions and biological efficacy in metabolic disease therapy." (PMID 41226200, 2025).
metabolic disease (continued). "Gut‐derived hormones are currently utilized in the clinical management of metabolic diseases, exemplified by glucagon‐like peptide‐1 receptor (GLP‐1R) agonists such as semaglutide and liraglutide, as well as GLP‐1/GIP (glucose‐dependent insulinotropic polypeptide) dual agonists like tirzepatide." (PMID 40529613, 2025). "These agonists activate GLP-1R, enhancing insulin secretion, inhibiting glucagon release, delaying gastric emptying, and suppressing appetite through central mechanisms, making them valuable therapeutic agents for metabolic disorder." (PMID 40001594, 2025). "Furthermore, it has been demonstrated that GLP-1R agonists act as a regulatory pathway that influences metabolic disorders." (PMID 40446026, 2025). "The abrupt cessation of GLP-1R agonists in individuals with metabolic disorders may lead to adverse effects, as seen in a case where a patient developed IIH after discontinuing duraglutide." (PMID 38997662, 2024). "Secondly, ligands or allosteric modulators that can also target the intracellular GLP1R pool might further increase efficacy of GLP1R agonists used in the treatment of metabolic disease." (PMID 34123074, 2020). "In light of this, novel combination therapies that aim to broaden the therapeutic potential of GLP-1R agonism may provide unique opportunities for optimum treatment of metabolic disorders." (PMID 25652173, 2015). "Conceptualizing GLP-1R as a dynamic architect of spatiotemporally encoded signalosomes opens new avenues for a deeper understanding of incretin biology with the potential for identification of novel GLP-1R effectors and the development of refined therapeutic strategies for metabolic disease." (PMID 41542774, 2026). "Given the accumulating evidence supporting the application of GLP1R agonists for the treatment of other disease states, including other metabolic diseases and numerous neurological disorders via mechanisms involving autophagy, these findings could have implications beyond the treatment of T2D." (PMID 34338148, 2022). "What factors shape how caregivers experiencing food insecurity perceive the use of glucagon-like peptide-1 receptor agonists (GLP-1 RAs) for children with obesity and metabolic disease?" (PMID 41499114, 2026). "One of the most promising classes of drugs for pediatric MASLD is glucagon-like peptide-1 receptor agonists (GLP-1 RAs), which have shown significant efficacy in treating obesity and related metabolic disorders." (PMID 41158823, 2025). "Several multi-agonists with GLP-1 receptor (GLP-1R) and glucagon receptor (GCGR) activity are currently being developed to treat metabolic disease." (PMID 36384093, 2022). "Indeed, the cross reaction of glucagon at the GLP-1R has proven to be vital for pancreas function and dual (or triple) agonists of the GCGR and GLP-1R (and GIP receptor) are currently being studied for the treatment of metabolic disorders." (PMID 36009454, 2022). "It is also unknown how much of resistance of endogenous signaling contributes to the heterogeneity observed in metabolic disease and the variable patient responses to pharmacological treatments including DPP4 inhibitors, GLP-1R agonists and bariatric surgery." (PMID 34660576, 2021). "Although both GLP-1R and irisin are considered to reduce metabolic disorder, it is not clear whether they generated these protective effects in cardiomyoblasts through distinctive pathways." (PMID 27875543, 2016).
cancer (94 papers, 2012 to 2026). A tumor composed of atypical neoplastic, often pleomorphic cells that invade other tissues. "GLP-1R expression has been associated with the prognosis of patients with varying malignancies, but the direction of association depends on the cancer type." (PMID 41178720, 2025). "Clinicians should consider the specific cancer risks associated with GLP-1R agonists and balance these against the benefits of glycemic control and weight loss." (PMID 39777709, 2025). "Given the varying effects of GLP1R expression on survival across different cancer types, the use of GLP-1 receptor agonists in obese or diabetic patients at high risk for cancer should be approached with caution." (PMID 39777709, 2025). "GLP-1R agonists are proposed to influence cancer risk and progression through multiple mechanisms, both indirectly and through direct action on cancer cells themselves." (PMID 41178720, 2025). "In conclusion, this study provides a nuanced view of the role of GLP1R expression in cancer survival, highlighting both protective and adverse associations depending on the cancer type." (PMID 39777709, 2025). "To date, almost all clinical studies on GLP-1R therapies and cancer describe risk as the primary outcome." (PMID 41178720, 2025). "When these cancer subtypes were combined, GLP-1R agonist use for T2D management reduced the risk for all hematologic malignancies by 54% compared with insulin." (PMID 41178720, 2025). "Future research should focus on elucidating the molecular mechanisms underlying the differential effects of GLP1R expression in various cancers." (PMID 39777709, 2025). "A recent study investigated the association of glucagon-like peptide-1 receptor agonists with cancers and illustrated the evidence of this glucose control drug with cancer risks." (PMID 39655224, 2024). "These Il6ra+ cells also partially overlapped with Gfral-expressing (Gfral+) neurons, a subpopulation of Glp1r+ neurons in the AP that have been implicated in nausea and cancer cachexia." (PMID 38824130, 2024). "There was little evidence to support associations between genetically proxied PPARG perturbation and colorectal or overall cancer risk or between genetically proxied ABCC8 or GLP1R perturbation with risk across cancer endpoints." (PMID 37171501, 2023). "There was little MR evidence of association of genetically proxied ABCC8 or GLP1R perturbation with site-specific or overall cancer risk." (PMID 37171501, 2023). "In conclusion, we developed novel instruments for PPARG, ABCC8 and GLP1R using strict validation protocols and evaluated the association of genetically proxied perturbation of these targets with risk of cancer." (PMID 37171501, 2023). "On the other hand, recent studies showed that the use of these GLP-1R agonists in anti-diabetic treatment can be associated with an increase of cancer risk." (PMID 23641235, 2013). "One recent study suggested that glucagon-like peptide 1 receptor agonists, anti-diabetic drugs which help weight loss, may lower cancer incidence." (PMID 40698288, 2025). "In patients with a high risk of cancers where GLP1R expression is associated with poor outcomes, alternative therapies might be more appropriate." (PMID 39777709, 2025). "GLP-1R therapies have emerged as potential effectors of cancer risk and prognosis." (PMID 41178720, 2025). "Here, we describe the available evidence that GLP-1R agonists may alter cancer risk, and the molecular mechanisms that may underlie the effect." (PMID 41178720, 2025). "Finally, we found little evidence for an association of genetically proxied ABCC8 and GLP1R perturbation with risk of breast, colorectal, prostate or overall cancer risk." (PMID 37171501, 2023). "Moreover, for many malignancies, there is evidence of an association between GLP1R activation and reduced cancer incidence." (PMID 38201269, 2023).
cancer (continued). "Although GLP1RA often cause super-physiological levels of GLP1R activation, this study provides evidence that GLP1R signaling may decrease cancer risk." (PMID 38201269, 2023). "In addition to hormone therapy with progestins, glucagon like peptide-1 receptor (GLP-1R) agonists such as semaglutide may be helpful to achieve weight loss during conservative treatment of endometrial hyperplasia or cancer." (PMID 40002193, 2025). "First, to define the spectrum of GLP-1R expression in a pan-cancer analysis the human Dependency Map (DepMap) cell lines (n=1684) were interrogated for GLP-1R transcript levels." (PMID 41542041, 2026). "In GLP-1 exposed tumors, malignant cells showed markedly increased spatial co-localization with macrophages, with cancer–macrophage niches accounting for 15% of all GLP-1R+ neighborhoods." (PMID 41542041, 2026). "Several planned or ongoing clinical trials will address GLP-1R therapy use in people diagnosed with cancer." (PMID 41178720, 2025). "Our findings contribute to filling this gap, demonstrating that glucagon’s interactions with both the GCGR and GLP-1R add complexity to its role in cancer biology, potentially driving adaptive mechanisms in pNET cells." (PMID 40649254, 2025). "While glucagon-like peptide-1 receptor agonists (GLP-1 RAs) have been demonstrated to be efficacious in weight control in non-cancer populations, to date, only one case report assessed the effect of GLP-1 RAs on alectinib-induced weight gain." (PMID 41357598, 2025). "This study aimed to evaluate the prognostic significance of GLP1R expression on overall survival across various cancer types." (PMID 39777709, 2025). "Bariatric surgery caused superior weight loss, but cancer risk was 40% lower in GLP-1R agonist users than in those who had bariatric surgery, suggesting weight loss–independent anticancer mechanisms of GLP-1R therapies." (PMID 41178720, 2025). "Future research should focus on integrating GLP1R signaling-related gene expression signatures with existing biomarkers to improve prognostic accuracy across multiple cancer types." (PMID 39777709, 2025). "These planned or ongoing clinical trials will provide important resources to validate potential mechanisms identified in preclinical studies of GLP-1R therapies, where cancer progression is often the primary endpoint." (PMID 41178720, 2025). "A common theme emerging from the preclinical studies of GLP-1R agonists and cancer is the potential to promote antitumor immune cell phenotypes, including in lean mice that were not given a high-fat diet." (PMID 41178720, 2025). "Given these considerations, future research should prioritize stratified analyses to delineate the age- and sex-specific impacts of GLP-1R agonists on cancer progression and survival." (PMID 39777709, 2025). "Given the diverse effects of GLP1R and GCG expression on cancer survival, clinicians should exercise caution when prescribing GLP-1 receptor agonists, particularly in patients with known cancer risks." (PMID 39777709, 2025). "GLP-1R deregulation has been identified in various cancer types, including thyroid cancer, pancreatic adenocarcinoma, and breast cancer." (PMID 40361517, 2025). "Beyond their well-documented metabolic benefits, there is a growing interest in the potential effects of GLP1R agonists on cancer biology." (PMID 39777709, 2025). "In clinical studies, there is growing need for trials that enroll patients being treated for cancer to investigate the effects of GLP-1R treatments in these unique populations." (PMID 41178720, 2025). "We analyzed the correlation between overall survival and GLP1R gene expression changes across various cancers." (PMID 39777709, 2025). "Because NENs are relatively rare cancers, little is known about GLP-1R expression in NENs from different anatomical locations or their response to semaglutide." (PMID 41312422, 2025).
cancer (continued). "Liraglutide and exendin-4 are initially antidiabetic drugs but can affect tumorigenesis, suggesting GLP-1R agonists as a potential treatment for different cancers as found in vivo." (PMID 38801466, 2024). "As such, through several potential mechanisms, pre-clinical data provide a rationale for the role of GLP-1R agonists in potentially treating several cancers." (PMID 39931650, 2024). "This calls for more extensive research to unravel the intricate relationships between the GLP-1R agonist and different cancers, providing valuable insights for clinicians and researchers alike." (PMID 38801466, 2024). "Although there is a lack of direct studies on semaglutide, the observed actions align with those of other GLP-1R agonists, indicating a potential impact on cancer." (PMID 38801466, 2024). "Pre-clinical and retrospective clinical data strongly support further investigation of GLP-1R agonists in either cancer prevention or in combination with chemotherapy in treating cancer." (PMID 39931650, 2024). "The investigation into GLP-1-R action mechanisms and signaling pathways in cancer cells has been a focal point for numerous researchers." (PMID 38672620, 2024). "Prospective clinical trials evaluating GLP-1R agonists in diabetes initially provided possible evidence for a role in cancer prevention." (PMID 39931650, 2024). "As such, randomized controlled trials are required to determine the clinical benefit of GLP-1R agonists in cancer prevention and treatment." (PMID 39931650, 2024). "While other GLP-1R agonists have shown promising outcomes in mitigating cancer progression, the association between some GLP-1R agonists and an increased risk of cancer remains a topic requiring more profound investigation." (PMID 38801466, 2024). "The research also investigated how the inhibition of GLP1R affects apoptosis in EC cells acanthosis nigricans 3rd attempt-carcinoma (AN3CA) and observed a decreased rate of apoptosis in AN3CA cells treated with a GLP-1 agonist compared to the control group." (PMID 39429275, 2024). "Considering these mixed data, it is crucial to better understand the role of GLP1R agonism in cancer as these drugs become more widely adopted." (PMID 38201269, 2023). "In physiology, the species difference in the expression of GLP-1R is also noteworthy and will play a role in the effect GLP-1R agonists (such as TRZD) on cancers." (PMID 36358930, 2022). "GLP-1R is more typically related to diabetes than cancers, but it also has implications for various cancers that especially include those effecting the pancreas." (PMID 33673713, 2021). "Recently, Wang Yongxiang and colleagues provided the first evidence that activation of microglial glucagon-like peptide-1 receptor (GLP-1R) in the spinal cord specifically suppresses neuropathic pain, cancer pain, and diabetic hypersensitivity." (PMID 34325647, 2021). "The GLP-1R overexpression in selected cancers is worth to be kept in mind with regard to the increasing use of GLP-1 analogs for diabetes therapy." (PMID 23230431, 2012). "This uncertainty raises an important question: could pharmacologic activation of GLP-1R alter cancer treatment response?" (PMID 41542041, 2026). "GLP-1 treatment of cancer cells activated survival pathways, drove proliferation, induced paclitaxel resistance and dampened cytokine secretion, effects that required expression of GLP-1R." (PMID 41542041, 2026). "Conversely, for patients at risk of cancers where GLP1R expression is protective, GLP-1 receptor agonists could be considered a beneficial option." (PMID 39777709, 2025). "New clinical trials will evaluate the effectiveness of GLP-1R therapies in the context of currently approved cancer treatments, which might reveal unique mechanisms of drug action and vulnerabilities of cancer cells at different stages of disease." (PMID 41178720, 2025).